CRP (C-reactive protein)
Diseases named in the same sentence as CRP in open-access papers (continued):
Sharing a sentence is not in itself a finding about the gene and the disease.
infection (continued). "In 98 ICU patients, neither calprotectin nor CRP showed a meaningful association with an adjudicated diagnosis of infection or ICU death." (PMID 42209889, 2026). "The study concluded that neither biomarker is sufficient for standalone diagnosis, but CRP’s longitudinal trends may better reflect infection progression." (PMID 40647525, 2025). "Serum markers are the most common and straightforward diagnostic method, and, for the examination of pyogenic spondylitis, high-sensitivity screening for infection becomes possible with elevated C-reactive protein (CRP) level and erythrocyte sedimentation rate (ESR)." (PMID 40943760, 2025). "However, CRP alone has limitations due to its delayed rise (within 6–12 h after the onset of infection), which reduces its sensitivity in the early phase of EOS." (PMID 40003700, 2025). "CRP, also often reported as a marker of infection or inflammation, was measured in 142 episodes." (PMID 40901476, 2025). "Elevated and persistent CRP levels indicate ongoing infection and may signal ineffective antibiotic therapy, necessitating timely treatment adjustments." (PMID 41462832, 2025). "A CRP level above 150.3 mg/dl, a CSF protein/glucose ratio of 18.9, and a CSF glucose level of 6.75 mg/dl collectively indicate a high bacterial load and extensive infection—strong predictors of the need for surgical intervention." (PMID 40740821, 2025). "CRP and procalcitonin are routinely used to detect infection or inflammation." (PMID 40143286, 2025). "CRP, for instance, is a widely used acute-phase biomarker; however, its delayed elevation—requiring 24–48 hours to peak—reduces its sensitivity in detecting early infections." (PMID 40895306, 2025). "Infection was based on documented signs and symptoms of infection, laboratory tests (white blood cell count, C-reactive protein, and procalcitonin) and microbiological analyses on admission, and on medical records stating the diagnosis and treatment of infection during admission." (PMID 39838391, 2025). "Observed decreases in HRV correlated with elevation of CRP level during the infection." (PMID 41462903, 2025). "CRP levels are frequently elevated in cancer patients due to infection or the malignancy itself." (PMID 40506552, 2025). "It was not possible to differentiate chikungunya infections from dengue infections based on clinical features or routine non-diagnostic laboratory tests conducted in early infection (e.g., full blood count, C-reactive protein level)." (PMID 40622975, 2025). "Additionally, blood procalcitonin and CRP (C-reactive protein) levels are elevated, partially dependent on the time course of infection; further parameters are a high blood neutrophil granulocyte count and a low thrombocyte count." (PMID 39961996, 2025). "Multiple studies have demonstrated that biomarkers such as IL-6, PCT, IL-10, and IL-8 offer superior sensitivity and specificity compared to conventional markers like CRP, particularly in the early phase of infection and in differentiating between bacterial and viral etiologies." (PMID 40647525, 2025). "However, when a patient develops an infection, the liver synthesises stress response proteins such as CRP, which in turn reduces the amount of ALB synthesis, leading to an increase in CRP/ALB ratio levels." (PMID 41019129, 2025). "CRP is a frequently used clinical marker in the diagnosis of infection." (PMID 40125102, 2025). "In our study, in accordance with the literature, we found that the group older than 65 could provide a higher CRP predictive value for the diagnosis of infection." (PMID 40125102, 2025). "Nevertheless, the findings are in line with a systemic review and metanalysis from 2018, that found that CRP-based algorithms could shorten antibiotic treatment duration in neonates with suspected infection." (PMID 41433251, 2025).
infection (continued). "The ROSIE model also incorporates other clinical variables, namely systolic blood pressure and oxygen saturation, which may contribute to the identification of serious infections, even in patients presenting with lower CRP levels." (PMID 40407567, 2025). "Furthermore, the cutoff values for the CRP level at admission were >6.74 mg/dL and >8.73 mg/dL for predicting the presence of infections that would hinder chemotherapy in patients with comorbidities and those without comorbidities, respectively." (PMID 40125102, 2025). "In 39 cases, a CRP value was also documented at the end of the hospitalization, although 5 complex treatments were additionally excluded from the evaluation because the children concerned had an infection." (PMID 40310131, 2025). "Its delayed response limits the utility of CRP as an early biomarker for detecting infections in HTx patients, suggesting that it may be more useful for monitoring later-stage complications." (PMID 40806991, 2025). "CRP, as an acute-phase reactant, is elevated in uncontrolled infection, while reduced platelet counts may indicate disseminated intravascular coagulation, bone marrow suppression, or consumption due to systemic inflammation." (PMID 40724002, 2025). "Additionally, the severity of MP infection metrics can include other factors (i.e., hospitalization duration, white blood cell count, CRP levels, LDH levels, and the frequency of steroid treatment)." (PMID 41012693, 2025). "Furthermore, the combination group faced more severe and complex infections, as evidenced by significantly higher CRP levels, a trend of higher incidence of fever, and lower occurrence of upper limb infections." (PMID 40995023, 2025). "The differences in TBSA, burn index (BI), infection indicators (leukocytes, C-reactive protein [CRP], and procalcitonin [PCT]), and renal function indicators (Scr, blood urea nitrogen [BUN], and cystatin C [CysC]) between the survival group and the death group were significant (p < 0.05)." (PMID 40590000, 2025). "C-reactive protein and albumin are both acute-phase reactive proteins synthesized by the liver, with C-reactive protein levels increasing and albumin levels typically decreasing during the course of infection or inflammation." (PMID 40303878, 2025). "The most used biomarker for infection is C-reactive protein (CRP)." (PMID 40156733, 2025). "In cases involving intratumoral hemorrhage or necrotic infection, systemic inflammatory markers—such as white blood cell count, C-reactive protein, and erythrocyte sedimentation rate—may be elevated." (PMID 41479796, 2025). "Patients treated with IL-6 blockade, for instance, may fail to show symptoms of an infection because fever and CRP production are suppressed, impeding diagnosis and treatment." (PMID 41041324, 2025). "After MP infection, they exert their biological effects by binding to specific receptors on the membrane of target cells and are closely related to the synthesis of biomarkers such as CRP." (PMID 40171163, 2025). "Since, in contrast to CRP, IL-6 already peaks within 24 hours from the start of surgery, we hypothesized that IL-6 would be superior to CRP in predicting postoperative infection on the first postoperative morning after pulmonary surgery." (PMID 40549692, 2025). "Pooled evidence from 46 pediatric studies confirms that IL-6, Il-8, procalcitonin, and CRP remain the most validated biomarkers for early infection detection in pediatric febrile neutropenia, though their clinical utility depends on rigorous contextual interpretation." (PMID 40647525, 2025). "This raises the possibility that our model might miss serious infections in this subgroup, as it relies heavily on CRP as a key predictor." (PMID 40407567, 2025).
infection (continued). "Our study demonstrates that the ROSIE model, incorporating three easily measurable predictors (systolic blood pressure, oxygen saturation, and C-reactive protein), provides good discriminative power for identifying serious infections in older adults presenting to the ED." (PMID 40407567, 2025). "While these indices have been validated in oncologic and cardiovascular cohorts, their limited utility in acute care likely reflects the variability of CRP and albumin in ED patients, where acute inflammatory conditions such as infection, trauma, and systemic inflammation are common confounders." (PMID 41300867, 2025). "Furthermore, following CsA administration, we observed significant elevations in two key infection biomarkers C-reactive protein (CRP) and procalcitonin (PCT)." (PMID 41394124, 2025). "It is released promptly into the bloodstream following neutrophil activation during infection, enabling early identification of the body’s inflammatory response, often before notable increases in conventional markers like C-reactive protein (CRP) and procalcitonin (PCT) occur." (PMID 40650251, 2025). "Interpreting CRP changes post-antibiotic adjustment is also complicated by CRP’s ~ 19-hour half-life and ~ 48-hour time to peak, meaning early CRP levels likely reflect prior therapy and infection dynamics." (PMID 40764898, 2025). "The postoperative trends in blood inflammatory markers (WBC, neutrophils, CRP) were similar between the Suture and Control groups, suggesting that the PGA material did not provoke an excessive inflammatory response or worsen the underlying infection." (PMID 40796143, 2025). "Regarding to inflammatory markers, plasma samples collected on 3–4 dpi showed that animals from the group receiving both live dpB and SARS-CoV-2 vaccine showed higher values (mg/mL) of D-dimer, CRP and iNOS when compared to infection SARS-CoV-2 vaccinated group (M-W; pb=0.042, pb=0.021, pb=0.003)." (PMID 40969767, 2025). "Serum CRP levels can reflect the presence of inflammation and infection in pigs." (PMID 40427247, 2025). "The present study investigated the situations wherein higher CRP levels could be considered as the manifestation of infection that might hinder chemotherapy procedures and aimed to determine a cutoff value that could predict infection." (PMID 40125102, 2025). "We tested the hypothesis that the amyloid-binding function of structurally altered CRP is required for CRP-mediated protection against prolonged infection." (PMID 40740789, 2025). "Ultimately, the most suitable labeling method was selected for its superior sensitivity in measuring CRP concentrations and its ability to accurately detect a broader range of CRP levels, thereby supporting more reliable inflammatory and infection level monitoring." (PMID 40277527, 2025). "However on day 7, any effect of CRP on day 28 fatigue was eclipsed by major events such as delayed cerebral ischaemia, post-surgical trauma, instrumentation, metabolic upset or infection, which are likely to be short-lived and reversible." (PMID 40746967, 2025). "Additionally, elevated C-reactive protein (CRP) levels—suggestive of infection or inflammation—were present in 34.9% (15/43) of cases, while 65.1% (28/43) had normal CRP values." (PMID 40723025, 2025). "CRP is a marker of systemic inflammation and severe infection." (PMID 40622101, 2025). "Traditional infection markers such as white blood cell count and C-reactive protein (CRP) are commonly used but may lack specificity in this context." (PMID 41281267, 2025). "Patients were subjected to PCT and CRP tests only when they showed signs of infection." (PMID 40590000, 2025). "Our recent study has shown that pre-infection of influenza virus compromises the CRP-mediated bactericidal immunity neutrophils in the lungs by impairing the expression of the complement receptor CR3 and thereby enhances the virulence levels of serotype-23F S. pneumoniae and type-b H. influenzae." (PMID 41214213, 2025).
infection (continued). "The levels of WBC and CRP also increased first and then decreased after infection." (PMID 41048939, 2025). "Although C-reactive protein (CRP) and procalcitonin (PCT) are commonly utilized biomarkers for infection assessment in clinical practice, their diagnostic performance for AA remains suboptimal, with sensitivity and specificity ranging from 67% to 97.8% and 31.9%–80%, respectively." (PMID 40406622, 2025). "While other markers like CRP may also be elevated in various inflammatory conditions, TNF-α is more closely associated with the presence of active infection." (PMID 41357523, 2025). "Early empirical treatment could suppress infection markers like PCT, CRP, and NLR, leading to an underestimation of their diagnostic value." (PMID 41281267, 2025). "However, standard infection biomarkers such as C-reactive protein (CRP) and procalcitonin (PCT) have limited reliability in this setting." (PMID 40863214, 2025). "In addition, inflammatory markers, including erythrocyte sedimentation rate and C-reactive protein, were evaluated to exclude the possibility of infection." (PMID 40104774, 2025). "Additionally, for the multivariable logistic regression models treating MDW and CRP as continuous variables, both remained significant predictors of newly diagnosed infection." (PMID 40460177, 2025). "Higher admission CRP correlates with deeper infections and longer hospital stay." (PMID 41556000, 2025). "A declining trend in CRP and PCT levels within the first 48–72 h after initiating therapy is generally associated with better outcomes, while persistently elevated or rising levels suggest ongoing infection, treatment failure, or a complicated course." (PMID 41153844, 2025). "Due to the underlying malignancy, the absolute value of CRP for the evaluation of intercurrent infections has not been fully defined in patients with cancer." (PMID 40125102, 2025). "For example, physicians might be more prone to prescribe antibiotics at low CRP levels to a patient with immunosuppression or a history of frequent infections." (PMID 39460385, 2025). "Both SAA and CRP rise markedly during infection, tissue injury, or inflammation; notably, SAA may promote angiogenesis by facilitating endothelial cell migration and proliferation." (PMID 41255770, 2025). "CRP is a well-established marker of inflammation and has been widely used to monitor infections." (PMID 40806991, 2025). "However, misinterpretation of CRP trends, such as assuming a single elevated reading equates to infection, can lead to unnecessary imaging, prolonged hospitalization, and antibiotic overuse, contributing to antimicrobial resistance." (PMID 40342430, 2025). "Studies have shown that the expression level of CRP is significantly correlated with the degree of activity of the inflammatory response, especially in the state of trauma or infection, and its dynamic changes can provide an objective basis for the quantitative assessment of the inflammatory state." (PMID 41050348, 2025). "In addition, the relationship between the kinetics of known stress and infection parameters (cortisol, interleukin 6, C-reactive protein) and skin antioxidant concentration in term and preterm infants needs to be examined." (PMID 40283089, 2025). "Laboratory markers of infection, including hematologic indices and markers of inflammation, such as C-reactive protein (CRP) and procalcitonin, have poor specificity and can be elevated due to non-infectious causes early in life, potentially leading to overtreatment with antibiotics." (PMID 40493423, 2025). "Independent variables were selected based on prior literature, including age, sex, Charlson Comorbidity Index (CCI), quick sequential organ failure assessment (qSOFA) score, infection setting, invasive device use, C-reactive protein (CRP) level, and appropriateness of empiric antimicrobial therapy." (PMID 41477397, 2025).
infection (continued). "In fact, prior work in abdominal surgery suggests that patients with sufficiently low CRP levels by postoperative day 3–4 have a very low probability of harboring serious infection, and thus early discharge may be considered safe in such cases." (PMID 41153812, 2025). "The admission CRP cutoff value for predicting infection that would prevent chemotherapy in all patients was ≥6.74 mg/dL with a sensitivity, specificity, positive predictive value, and negative predictive value of 91.3%, 86.6%, 50%, and 98.6%, respectively (p<0.001)." (PMID 40125102, 2025). "Among baseline infection characteristics, CRP levels (OR = 1.01; 95% CI, 1.00–1.01; P = 0.008), and fever (OR = 3.11; 95% CI, 1.47–6.71; P = 0.003) were significantly associated with treatment failure, though only fever remained significant in multivariate and adjusted models." (PMID 40995023, 2025). "Among the most commonly used are C-reactive protein (CRP), utilized for inflammation; procalcitonin, utilized for infection; troponin T (TnT), utilized for myocardial necrosis; and, most notably, the amino-terminal fragment of B-type natriuretic peptide (NT-proBNP), utilized for myocardial stress." (PMID 40141838, 2025). "CRP is an acute phase protein synthesized by the liver in response to pro-inflammatory cytokines (primarily interleukin-6) released during tissue injury, infection, or other inflammatory stimuli." (PMID 41153812, 2025). "Currently, the application of NLR and CRP/ALB ratio in predicting early infection after open fracture and bone arthroplasty has been investigated, however, they have been relatively less studied in the prediction of postoperative infections in patients with spinal disorders." (PMID 41019129, 2025). "The CRP cutoff value to be considered for predicting infection was calculated." (PMID 40125102, 2025). "The Chinese Medical Association suggests that infection-related laboratory indicators, including PCT and CRP, should be completed within 3 h for patients with suspected bloodstream infections to determine whether infectious diseases exist." (PMID 40450236, 2025). "When we considered the infection variable as a dichotomous variable (infection present/ absent) and applied the Mann-Whitney test, we obtained extremely significant differences in the IL-6 and CRP values." (PMID 40242671, 2025). "When there is an infection or inflammation in the acute phase, CRP levels rise sharply." (PMID 40191419, 2025). "PCT and CRP are commonly employed to evaluate infection and inflammation." (PMID 41251102, 2025). "To assess whether missingness reflected outcome-dependent test ordering, we modeled the presence of four representative laboratory tests: C-reactive protein (CRP), creatinine, platelets, and alkaline phosphatase, using infection status as a predictor." (PMID 40886713, 2025). "In conclusion, early postoperative plasma IL-6 and CRP concentrations are independently associated with subsequent infection risk, although neither biomarker improved prognostic classification by a simple prediction model using readily available clinical data." (PMID 40549692, 2025). "Therefore, CRP levels measured in delayed hours after birth are more predictive of neonatal infections compared to those measured immediately after birth." (PMID 40809608, 2025). "However, CRP is synthesized by the liver and is seen to be elevated only slightly even in patients with an active infection." (PMID 40114845, 2025). "Infection was documented in six (54%) cases of these CRP outliers." (PMID 40208300, 2025). "This study confirms that C-reactive protein level, fasting blood glucose level, lactate dehydrogenase level, ECOG score, and the percentage of bone marrow plasma cell percentage are significant risk factors for infection in patients with MM." (PMID 41551150, 2025).